SOX2 (SRY-box transcription factor 2)
Diseases named in the same sentence as SOX2 in open-access papers (continued):
Sharing a sentence is not in itself a finding about the gene and the disease.
lymph node metastasis (35 papers, 2011 to 2025). "Accumulating evidence suggests that SOX2 promotes cancer cell stemness, and its overexpression is associated with lymph node metastasis and poor prognosis in cancer patients." (PMID 38566201, 2024). "Studies on head and neck SCC also demonstrated a significant association between SOX2 expression and lymph node metastasis." (PMID 31244283, 2019). "Through a univariate analysis, using a SOX2 mRNA cutoff level of 1.00 (relative to XpressRef Universal Total RNA, Qiagen), a high SOX2 mRNA expression level was strongly associated with lymph node metastasis (p < 0.001)." (PMID 26540632, 2016). "In conclusion, our study provides evidence that USP22 expression is associated with histological subtype, lymph node metastasis, grade, Ki-67 and SOX2 expression in SACC patients, and also is an independent prognostic factor for SACC." (PMID 24466336, 2014). "The multivariate analysis, adjusting for age, PSA levels and Gleason score, showed that the increase in SOX2 mRNA expression was significantly associated with the presence of lymph node metastasis (OR = 1.83 for each 1 unit increase in SOX2 mRNA expression; 95% CI: 1.43–2.35)." (PMID 26540632, 2016). "Additionally, SOX2 is also associated with lymph-node metastases." (PMID 22168803, 2011). "For SOX2 we have as well lower H‐Scores in lymph node metastases but the difference failed in significance." (PMID 39180200, 2025). "Meanwhile, patients with high expression of PP1γ, YAP1, and SOX2, tumor invasion depth, lymph node metastasis, advanced AJCC stage, and nerve invasion had significantly shorter PFS (P < 0.05)." (PMID 40626009, 2025). "The sole consideration of SOX2 expression only showed a tendency towards less lymph node metastasis and only the analysis in conjunction with SOX9 indicated the association with lower metastasis." (PMID 39180200, 2025). "SOX2 expression was significantly correlated with pathological grade, lymph node metastasis, AJCC stage, tumor size, and VM formation (Supplement Table." (PMID 32144236, 2020). "Nonetheless, the opposite viewpoint is represented by patients with early-stage OSCC, where upregulation of SOX2 has been correlated with a lower incidence of lymph node metastasis." (PMID 31640140, 2019). "It has been shown that SOX2-positive tumors, maintain such characteristic during lymph node metastasis." (PMID 31244283, 2019). "The correlation analysis further revealed that SOX2 expression correlated with lymph node metastasis." (PMID 30510261, 2018). "Univariate analysis revealed that tumor depth (P = 0.0003), lymph node metastasis (P = 0.001), venous invasion (P = 0.026), and Sox2 expression (P = 0.023) were significant prognostic factors." (PMID 30518951, 2018). "High expression of USP22 was significantly correlated with histological subtype, lymph node metastasis, grade, Ki-67 and SOX2 expression." (PMID 24466336, 2014). "Similarly, SOX2 and NANOG expression were both significantly associated with lymph node metastasis (P < 0.01) and advanced AJCC stage (P = 0.016 and P = 0.031, respectively)." (PMID 40626009, 2025). "Additionally, survival analysis showed that patients with high expression of YAP1 and SOX2, male gender, lymph node metastasis, and advanced AJCC stage had significantly shorter OS (P < 0.05)." (PMID 40626009, 2025). "It has been reported that a high expression of SOX2 was significantly associated with poorer survival in node-negative OSCC, while others found that a high expression of SOX2 correlated with lymph node metastasis." (PMID 31640140, 2019). "Higher expression of SOX2 was related to a greater possibility of lymph node metastasis." (PMID 30470250, 2018).
lymph node metastasis (continued). "The results showed that USP22 expression was correlated with histological subtype, lymph node metastasis, grade, Ki-67 and SOX2 expression, and the status of USP22 expression could be predictive factors of SACC." (PMID 24466336, 2014). "However, similar to β-catenin combined scores of high SOX2 and high CD133 showed strong predictive value according to the risk of distant spread (8 of 10 cases; 80%) and the presence of lymph-node metastases (9 of 10 cases; 90%)." (PMID 22168803, 2011). "Samples from 95 patients diagnosed and treated at the University of Tuebingen Institute of Pathology and Women's Hospital were analyzed by immunohistochemistry for SOX2 expression in the primary tumor samples and in corresponding lymph node metastasis, where present." (PMID 21276239, 2011). "However, other groups have reported that high expression of SOX2 is associated with absence of lymph node metastasis and a better prognosis in patients with OSCC, and also with improved clinical outcome in HNSCC patients treated with chemoradiotherapy." (PMID 32635524, 2020). "Other commonly used biomarkers, such as Sox2, CD44, were also found to be correlated with clinical characteristics of HNC, such as staging, tumor size and lymph node metastasis." (PMID 32357409, 2020). "Lower levels of FOXO3a, and higher levels of FOXM1, SOX2, or DNMT1 were correlated with shorter survival in the lymph node metastasis positive subgroup." (PMID 31296961, 2020). "In these SOX2 positive CRC tumors, the percentage of liver and lymph node metastasis were 77.8% and 88.8% (7/9 and 8/9 cases) respectively." (PMID 22912670, 2012). "We found a positive relationship between Sox-2 overexpression and lymph node metastasis as well as OS, but not with DFS/RFS." (PMID 33639931, 2021). "Moreover, high levels of FOXM1, SOX2, and DNMT1 were correlated with high histological grade, advanced clinical stage, and lymph node metastasis." (PMID 31296961, 2020). "In this study, we observed that the expression of SOX2, but not OCT4 and NANOG, correlates with poor histological differentiation of endometrial tumors, associates with lymph node metastasis, and predicts a poor survival in patients." (PMID 30510261, 2018). "In our cohort, SOX2 was detected in 14 out of 45 (31%) samples and was significantly higher in patients without lymph node metastasis at initial diagnosis; only one patient with a SOX2positive tumor showed positive lymph nodes." (PMID 29596469, 2018). "Otherwise, about the group with SOX2 upregulation or increased CD204+ macrophages (staining score in intralymphatics increased more than double in primary tumors), the frequency of lymph node metastasis was almost equivalent than other cases (p = 0.440 and 0.584, respectively)." (PMID 24376714, 2013). "However, we did not see a clear correlation of SOX2 expression and lymph node metastases by chi‐square testing and cross‐tabulation and we found no significant impact of SOX2 on overall survival." (PMID 39180200, 2025). "Several studies have also reported an enhanced expression of the stem cell markers CD44, ALDH1, c-Met, Oct3/4 and SOX-2 in primary tumours of patients with lymph node metastasis compared to those with negative lymph nodes, although the differences were not always statistically significant." (PMID 34831291, 2021). "In conclusion, the current study suggested that SOX2 expression was not significantly correlated with age, gender, MSI status, clinical stage, histological grade, tumor size, pT-stage, lymph node metastasis, distal metastasis, and CSS but was associated with worse OS and DFS." (PMID 32104175, 2020). "Interestingly, SOX2 expression was significantly higher in patients without lymph node metastasis as compared to their N+ counterparts (p = 0.047), and a clear trend of higher SOX2 expression in patients with a lower tumor stage (p = 0.067) was observed." (PMID 29596469, 2018).
lymph node metastasis (continued). "In our study, expression of OCT4, SOX2 and NANOG genes was slightly, but not significantly, higher in patients without lymph node metastasis." (PMID 31244283, 2019). "However, in the SOX2 negative CRC tumors, the percentage of liver and lymph node metastasis were 40.0% and 51.4% (14/35 and 18/35 cases) respectively." (PMID 22912670, 2012).
nasopharyngeal carcinoma (32 papers, 2010 to 2025). A carcinoma arising from the nasopharyngeal epithelium. "In nasopharyngeal carcinoma CSCs, SOX2 expression was associated with high risk of tumor progression and metastasis." (PMID 38612911, 2024). "Together, these results strongly indicate that upregulation of SOX2 was closely associated with tumor progression and poor prognosis in nasopharyngeal carcinoma patients." (PMID 30108202, 2018). "SOX2 expression was associated with nasopharyngeal carcinoma patient survival." (PMID 30108202, 2018). "SEs commonly achieve target gene activation through long-range chromatin looping, exemplified by MYC regulation in epithelial cancers via SE-driven chromatin architecture and SUCLG2-AS1 transcript-mediated SOX2 control in nasopharyngeal carcinoma." (PMID 40941410, 2025). "This remote interaction increases the transcriptional activation of SOX2 and promotes invasion and metastasis of nasopharyngeal carcinoma (NPC)." (PMID 39690143, 2024). "Underscoring these numbers, 699 significantly modulated SOX2 downstream targets were more recently identified in nasopharyngeal cancer cells by cDNA microarray." (PMID 31477842, 2020). "The transcription factor SOX2 induces the expression of lncRNA ANRIL by promoting its transcription in nasopharyngeal carcinoma cells." (PMID 33520999, 2020). "First, it moderately downregulated the p110α level, leading to a slight reduction in the P-AKT level, which is in line with a previous study on nasopharyngeal carcinoma showing that Sox2 can activate AKT by inducing the transcription of the PIK3CA gene." (PMID 33228022, 2020). "Subsequently, we examined the protein expression of stem cell markers, including Nanog, sox2, and Oct4, in nasopharyngeal carcinoma cell lines." (PMID 31889900, 2019). "CD24high human nasopharyngeal carcinoma cells express stem cell genes (Sox2, Oct4, Nanog, and Bmi-1) with Wnt/β-catenin signaling activation." (PMID 30467381, 2019). "Taken together, these results demonstrated that transcription factors SOX2 regulates cell proliferation in nasopharyngeal carcinoma through the PI3K/AKT signaling pathway." (PMID 30108202, 2018). "In conclusion, the activation of the WNT/β-catenin pathway is mediated by the SOX2-ANRIL pathway in nasopharyngeal carcinoma." (PMID 29463902, 2018). "Collectively, these results indicate that ANRIL is critical for SOX2-induced nasopharyngeal carcinoma growth." (PMID 29463902, 2018). "In current study, SOX2 oncogenicity was further highlighted by the finding that SOX2 gene was upregulated in nasopharyngeal carcinoma based on the data derived from GEO and TCGA database." (PMID 30108202, 2018). "Compared with the control xeno-graftmodels, knockdown of SOX2 significantly inhibited nasopharyngeal carcinoma tumor growth." (PMID 30108202, 2018). "In contrast, SOX2 was expressed strongly in the nasopharyngeal carcinoma tissues, suggesting that the levels of SOX2 expression are upregulated in tumor tissues." (PMID 30108202, 2018). "In this study, we are the first to report that SOX2-induced ANRIL promotes nasopharyngeal carcinoma growth by promoting β-catenin." (PMID 29463902, 2018). "We confirmed that SOX2 functions as a critical molecule in the regulation of human nasopharyngeal carcinoma." (PMID 29463902, 2018). "In order to determine the role of SOX2 in nasopharyngeal carcinoma, the expression level of SOX2 in clinical specimens of patients was examined." (PMID 30108202, 2018). "Kaplan–Meier survival analysis revealed a statistically significant worse prognosis for nasopharyngeal carcinoma patients with high SOX2 protein levels compared with those with low." (PMID 30108202, 2018). "Expression levels of ANRIL are positively correlated with SOX2 and β-catenin in clinical nasopharyngeal carcinoma samples." (PMID 29463902, 2018). "The levels of ANRIL were positively correlated with those of SOX2 and β-catenin in nasopharyngeal carcinoma tissues." (PMID 29463902, 2018).
nasopharyngeal carcinoma (continued). "Here, we report that upregulation of the expression of the SOX2-activated lncRNA ANRIL is involved in nasopharyngeal carcinoma." (PMID 29463902, 2018). "The results in the two nasopharyngeal carcinoma lines showed that the complexes immunoprecipitated by the two anti-SOX2 antibodies were enriched in the ANRIL promoter DNA fragment, compared with the isotype antibody control." (PMID 29463902, 2018). "Next, the correlation assay was performed between the expression of ANRIL and SOX2 in 20 nasopharyngeal carcinoma tissues." (PMID 29463902, 2018). "Here, we identify a SOX2 signaling pathway that facilitates nasopharyngeal carcinoma, where it is upregulated." (PMID 30108202, 2018). "Our data, taken together, demonstrated that SOX2 functions as an important oncogene in nasopharyngeal carcinoma." (PMID 30108202, 2018). "Six hundred and ninety-nine candidate SOX2 downstream dysregulated genes were identified in nasopharyngeal carcinoma cells through cDNA microarray analysis." (PMID 30108202, 2018). "To further validate that SOX2 upregulates PIK3CA expression thereby activating PI3K/Akt signaling pathways in nasopharyngeal carcinoma, we overexpressed PIK3CA in HNE-1 nasopharyngeal carcinoma cells with SOX2 shRNAs or a control shRNA." (PMID 30108202, 2018). "Knockdown of SOX2 by shRNAs inhibited nasopharyngeal carcinoma cell proliferation in vitro, and nasopharyngeal carcinoma tumorigenicity in vivo." (PMID 30108202, 2018). "Knockdown of endogenous SOX2 significantly suppress cell proliferation and colony formation in both nasopharyngeal carcinoma cell lines." (PMID 30108202, 2018). "Overall, these data demonstrate that SOX2 regulates AKT activity to promote nasopharyngeal carcinoma cell proliferation." (PMID 30108202, 2018). "We downloaded one nasopharyngeal carcinoma microarray data sets, GSE53819, and examined SOX2 mRNA expression in clinical nasopharyngeal carcinoma samples and normal nasopharyngeal tissues." (PMID 30108202, 2018). "In the current study, we found that SOX2 was genetically overexpressed both in clinical nasopharyngeal carcinoma tissues and cell lines." (PMID 30108202, 2018). "Both in vitro and in vivo studies showed that SOX2 exhibits a critical oncogene to regulate proliferation and tumorigenesis in nasopharyngeal carcinoma." (PMID 30108202, 2018). "Above, data definitely support that SOX2 is critical for cell proliferation, and tumor growth in nasopharyngeal carcinoma." (PMID 30108202, 2018). "Our findings demonstrate that the SOX2-ANRIL-β-catenin axis plays a critical role in nasopharyngeal carcinoma proliferation and provide a potential therapeutic approach for nasopharyngeal carcinoma patients." (PMID 29463902, 2018). "For example, miR-30a, when upregulated in nasopharyngeal carcinoma cells, appears to be capable of reducing SOX2 protein by targeting the 3’ UTR of SOX2 mRNA." (PMID 28388544, 2017). "Additionally, METTL3 stabilizes the super-enhancer lncRNA SUCLG2-AS1, facilitating the formation of a long-range chromatin loop between the SOX2 enhancer and promoter, which promotes nasopharyngeal carcinoma metastasis and radiation insensitivity." (PMID 41390674, 2025). "Additionally, METTL3 enables nasopharyngeal carcinoma cells to resist apoptosis after radiation by mediating the SUCLG2-AS1/CTCF/SOX2 axis." (PMID 38473842, 2024). "Consequently, SUCLG2-AS1 binds to the SE region of SOX2 to regulate SOX2 transcription, contributing to metastasis and radioresistance of nasopharyngeal carcinoma." (PMID 38473842, 2024). "Evidence suggests that SOX2 could upregulate β‐catenin signalling, thus regulating metastasis of nasopharyngeal carcinoma." (PMID 37658588, 2023). "Furthermore, the involvement of genes in the PI3K/AKT pathway in SOX2 regulation in breast and nasopharyngeal carcinoma has recently been reported." (PMID 33445526, 2021). "ANRIL could rescue the suppressive effects of SOX2 knockdown on nasopharyngeal carcinoma cell proliferation." (PMID 29463902, 2018).